MIR4529 (microRNA 4529)
Synonyms: hsa-mir-4529
Gene: MicroRNA gene on chromosome 18 (55,479,221 to 55,479,298, forward strand). Ensembl gene ENSG00000264571.
Homologues: Orthologues: chimpanzee MIR4529 (100% identical).